CIDEB (cell death inducing DFFA like effector b)
Description:
Lipid transferase specifically expressed in hepatocytes, which promotes unilocular lipid droplet formation by mediating lipid droplet fusion. Lipid droplet fusion promotes their enlargement, restricting lipolysis and favoring lipid storage. Localizes on the lipid droplet surface, at focal contact sites between lipid droplets, and mediates atypical lipid droplet fusion by promoting directional net neutral lipid transfer from the smaller to larger lipid droplets (By similarity). The transfer direction may be driven by the internal pressure difference between the contacting lipid droplet pair (By similarity). Promotes lipid exchange and lipid droplet fusion in both small and large lipid droplet-containing hepatocytes (By similarity). In addition to its role in lipid droplet fusion, also involved in cytoplasmic vesicle biogenesis and transport (By similarity). Required for very-low-density lipoprotein (VLDL) lipidation and maturation (By similarity). Probably involved in the biogenesis of VLDL transport vesicles by forming a COPII vesicle coat and facilitating the formation of endoplasmic reticulum-derived large vesicles (By similarity). Also involved in sterol-regulated export of the SCAP-SREBP complex, composed of SCAP, SREBF1/SREBP1 and SREBF2/SREBP2, by promoting loading of SCAP-SREBP into COPII vesicles (By similarity). May also activate apoptosis. (Microbial infection) Involved in Hepatatis C virus (HCV) assembly and required for HCV entry into hepatocytes.
Tractability: Antibody: UniProt places it where antibodies can reach, with medium confidence. PROTAC: its protein half-life has been measured.
Gene: Protein-coding gene on chromosome 14 (24,305,187 to 24,311,440, reverse strand). Ensembl gene ENSG00000136305.
Subcellular location: Lipid droplet; Endoplasmic reticulum membrane; Golgi apparatus; Cytoplasmic vesicle, COPI-coated vesicle
Subcellular location (Human Protein Atlas): Golgi apparatus; Vesicles
Gene Ontology:
Molecular function: identical protein binding; protein binding; lipid transfer activity; molecular adaptor activity; phosphatidic acid binding
Biological process: apoptotic process; lipid droplet fusion; positive regulation of apoptotic process; COPII-coated vesicle cargo loading; execution phase of apoptosis; intrinsic apoptotic signaling pathway in response to DNA damage; lipid storage; regulation of triglyceride metabolic process; very-low-density lipoprotein particle assembly; intermembrane lipid transfer; response to nutrient levels
Cellular component: cytosol; lipid droplet; perinuclear region of cytoplasm; COPII vesicle coat; endoplasmic reticulum; endoplasmic reticulum membrane; Golgi apparatus; COPI-coated vesicle; cytoplasm
Genetic constraint (gnomAD): Loss-of-function variants: 31 observed, 27.11 expected, observed/expected ratio (o/e) 1.14, 90% interval 0.86 to 1.54. The upper end of that interval is the gene's LOEUF score, 1.54, which puts it in group 6 of 6, group 1 being the genes least tolerant of losing a copy. Missense variants: 289 observed, 279.51 expected, observed/expected ratio (o/e) 1.03, 90% interval 0.94 to 1.14. Synonymous variants: 103 observed, 114.87 expected, observed/expected ratio (o/e) 0.9, 90% interval 0.76 to 1.06.
Homologues: Orthologues: chimpanzee CIDEB (99% identical), macaque CIDEB (97% identical), dog CIDEB (89% identical), rabbit CIDEB (87% identical), guinea pig CIDEB (86% identical), mouse Cideb (85% identical), pig CIDEB (85% identical), rat Cideb (84% identical), tropical clawed frog cideb (58% identical), zebrafish cideb (46% identical), Drosophila melanogaster Drep2 (26% identical). Paralogues in human: CIDEC (41% identical), CIDEA (40% identical), DFFA (25% identical).
Diseases named in the same sentence as CIDEB in open-access papers:
CIDEB is named in the same sentence as 21 diseases in open-access papers, as found by Europe PMC text mining. Sharing a sentence is not in itself a finding about the gene and the disease. The quoted sentences say what the papers report.
liver disease (6 papers, 2022 to 2026). "Collectively, these studies suggest that CIDEB mutations are protective against lipotoxic liver disease." (PMID 40618957, 2026). "Somatic and germline CIDEB mutations appear to ameliorate liver disease in humans 1,2." (PMID 40618957, 2026). "Further investigation is warranted to elucidate the mechanisms of CIDEB in lipid droplet formation and to understand how its loss of function may decrease liver disease risk and, consequently, HCC risk." (PMID 38163482, 2023). "We then asked if Cideb deficient clone selection was more pronounced in certain types of liver disease, and determined if this information might provide clues about the molecular basis for CIDEB's effects." (PMID 40618957, 2026).
Hepatic steatosis (5 papers, 2016 to 2026). Steatosis is a term used to denote lipid accumulation within hepatocytes. "We first evaluated the hepatic expression levels of CIDEA, CIDEB and FSP27α and β in dietary mouse models of obesity and hepatic steatosis." (PMID 31097771, 2019). "The mechanistic basis and whether CIDEB suppression would be an effective therapy against fatty liver disease remain unclear." (PMID 40618957, 2026). "Studies in CIDEB−/− mice have also confirmed that CIDEB plays a multifunctional role in controlling hepatic lipid secretion, storage, and synthesis, preventing diet‐induced obesity, insulin resistance, hepatic steatosis, and inflammation." (PMID 38344397, 2024). "Even though it is robustly expressed in the liver (data not shown), hepatic expression of CIDEB did not change with obesity or hepatic steatosis." (PMID 31097771, 2019).
Obesity (5 papers, 2019 to 2025). Accumulation of substantial excess body fat. "In mice, the up-regulated expression of SREBP1 promoted the lipid fat metabolism and the secretion of VLDL, while the CIDEB deficiency cancelled the diet-induced obesity via the significantly decreased of SREBP1." (PMID 40045630, 2025). "This study is the first to report the association of the CIDEB gene promoter methylation level with overweight or obesity in abdominal adipose tissue of adults, which is a significant exploration to elucidate the epigenetic mechanism of obesity development." (PMID 35475772, 2022). "We found that 3 haplotypes were related to overweight or obesity, which indicated that regulation of CIDEB expression is not a single-site mutation, but a combination of multiple-site mutations." (PMID 35475772, 2022). "The study found that CIDEB-null mice displayed significantly increased body metabolism, which could resist obesity and liver fat degeneration induced by high-fat diet." (PMID 35475772, 2022). "CIDEB promoter methylation level in abdominal SAT and OAT was detected by the MethylTarget technology, then its relationship with overweight or obesity was analyzed." (PMID 35475772, 2022). "The methylation level of CIDEB gene promoter in abdominal SAT and OAT may be related to overweight or obesity in adults, and the specific regulatory mechanism needs to be further studied." (PMID 35475772, 2022). "Our study found that methylation value of each CpG site of CIDEB gene in overweight/obesity group was higher than that of normal-weight group, but there was no statistical difference." (PMID 35475772, 2022). "Consistent with our animal results, the CIDEB expression was not modified with obesity and NAFLD in human studies." (PMID 31097771, 2019). "The study on the methylation level of CIDEB gene promoter in obesity has not been reported." (PMID 35475772, 2022). "Finally, we also report that the hepatic expression of CIDEB (at the mRNA level) is independent of obesity, as previously reported, and also independent of hepatic steatosis and steahepatitits in mouse and human studies." (PMID 31097771, 2019).
leukaemia (2 papers, 2010). "Some of these AM genes are known to be dysregulated in leukaemia: up regulation of BIRC3 and down regulation of APAF1, CIDEB, FAS, TNFRSF25, TNFSF10 were previously identified by our group as specific alterations of AM genes in leukemic cells." (PMID 20642818, 2010). "In the past, we showed that ART induced apoptosis in KG-1a leukemia cells, and that a number of apoptosis-regulating genes (LOC51272, CIDEB, PDCD2, BAG1, BAG3, MADD) correlated with cellular responses towards ART." (PMID 20428086, 2010).
Alzheimer disease (1 paper, 2025). A progressive, neurodegenerative disease characterized by loss of function and death of nerve cells in several areas of the brain leading to loss of cognitive function such as memory and language. "For CIDEB silencing, a total of 2140 DEGs were found, including 1252 up-regulated and 888 down-regulated DEGs, and the top three significantly changed pathways filtered by KEGG analysis were Ribosome, Thyroid hormone signaling pathway and Alzheimer disease." (PMID 40045630, 2025).
Cirrhosis (1 paper, 2022). A chronic disorder of the liver in which liver tissue becomes scarred and is partially replaced by regenerative nodules and fibrotic tissue resulting in loss of liver function. "Genome‐wide association study (GWAS) summary statistics were extracted from seven studies (>1.7 million participants) for variants near ACVR2A, ALB, CIDEB, FOXO1, GPAM, NEAT1 and TNRC6B for: aminotransferases, liver fat, HbA1c, diagnosis of NAFLD, ARLD and cirrhosis." (PMID 35474605, 2022).
Cocaine addiction (1 paper, 2025). "We also found significant changes in the malaria, taurine and hypotaurine metabolism, amphetamine addiction and cocaine addiction after overexpression of CIDEB by enrichment analysis of the differential gene KEGG pathway." (PMID 40045630, 2025).
hepatocellular carcinoma (1 paper, 2024). A malignant tumor that arises from hepatocytes. "Based on these studies, the researchers investigated the mechanism of the CIDEB mutation by siRNA silencing of the CIDEB gene in a human hepatocellular carcinoma cell line to mimic LOF and found that the mutation prevented fat from accumulating in the hepatocytes and produced smaller LD." (PMID 38344397, 2024).
hypertriglyceridemia (1 paper, 2025). A laboratory test result indicating elevated triglyceride concentration in the blood. "This study confirms that APOA5 rs2075291 and CIDEB rs2144492 polymorphisms are associated with hypertriglyceridemia." (PMID 41179497, 2025). "Our findings confirm that polymorphisms at the APOA5 rs2075291 and CIDEB rs2144492 loci are associated with hypertriglyceridemia." (PMID 41179497, 2025). "This study reports for the first time the association between APOA5 rs2075291 and CIDEB rs2144492 polymorphisms and hypertriglyceridemia in a dampness syndrome population, offering critical insights for investigating triglyceride metabolism in TCM dampness syndrome cohorts." (PMID 41179497, 2025). "APOA5 rs2075291 and CIDEB rs2144492 polymorphisms are associated with hypertriglyceridemia." (PMID 41179497, 2025).
liver cancer (1 paper, 2026). An epithelial or non-epithelial malignant neoplasm that arises from the liver. "Finally, therapeutic modeling shows that liver-specific CIDEB suppression can ameliorate late stage manifestations of the disease such as fibrosis and liver cancer." (PMID 40618957, 2026).
melanoma (1 paper, 2024). A malignant, usually aggressive tumor composed of atypical, neoplastic melanocytes.
metastatic disease (1 paper, 2021). "However, in subsequent metastatic disease (Mets2), methylation decreased to lower levels for the specific DMRs identified (which included probes for DAXX, LTB4R & CIDEB) in both cases." (PMID 33436720, 2021).
steatosis (1 paper, 2019). Increased lipid within the cytoplasm of cells. "To address the human relevance of our findings, we examined the relationship between hepatic CIDEA, CIDEB, CIDEC1 and CIDEC2 expression and the NAFLD progression from normal liver to steatosis and subsequent NASH in human liver biopsies from morbidly obese patients seeking for bariatric surgery." (PMID 31097771, 2019).
cancer (3 papers, 2013 to 2025). A tumor composed of atypical neoplastic, often pleomorphic cells that invade other tissues. "ACSL3, AIFM2, HSD17B7, LPCAT1, LSS, PLIN3 and RAB10 were up-regulated with the progression of cancer stage of HCC patients, while CIDEB, G0S2, HSD17B13, PLIN1 and PLIN2 were down-regulated." (PMID 37464334, 2023).
tumor (2 papers, 2017 to 2023). "The following marker genes were differentially expressed in the triphasic tumours relative to the blastemal tumours: PA (LHX1), RV/CSB/SSB (BMP2, CDH6, JAG1, PAPSS2), ePT and/or imHL (CIDEB, CLIC6, UNC5CL, VDR), and early DT/imHL (KCNJ1)." (PMID 29040332, 2017).
infection (1 paper, 2016). The state of being infected such as from the introduction of a foreign agent such as serum, vaccine, antigenic substance or organism. "Consistent with a previous report, CIDEB silencing did not affect HCV pseudoparticle (HCVpp) infection but did affect HCVcc entry." (PMID 27282740, 2016).
CIDEB also shares sentences with these, for which no sentence is quoted: Allergy (1 paper); diabetes (1); HCMV infection (1); Insulin resistance (1); metabolic dysfunction-associated steatotic liver disease (1).